CD68 (CD68 molecule)
Diseases named in the same sentence as CD68 in open-access papers (continued):
Sharing a sentence is not in itself a finding about the gene and the disease.
tumor (continued). "Although some of the IHC findings raised the possibility of a HS, as the tumour was also positive for CD68 and lysozyme, the morphology was not typical as the cells found in HS are large to round with focal spindling." (PMID 36344905, 2023). "CD68 itself is non-specific to either sub-type, though it has been shown to be from the M1 anti-tumor sub-type in higher proportions in double-stained experiments." (PMID 37488490, 2023). "Then, to investigate whether macrophages were recruited in TME by A549S25E cells showing high expression of VEGFA and IL1A, mouse tumor tissues were stained with specific macrophage antibodies for TAM marker CD163 and pan-macrophage marker CD68." (PMID 37968723, 2023). "Although we did not discover any correlation between total CD68+ TAMs and total CD3+ T cell as well as its CD4+ and CD8+ subgroups, we found that CD206+ TAMs were closely associated with CD4+ tumor-infiltrating T lymphocytes." (PMID 36864443, 2023). "In contrast, the number of total CD68+ cells in the tumor or stromal compartments was similar between pCR and nonpCR cases." (PMID 37284197, 2023). "Immunohistochemical analysis revealed a significant increase in intratumoural infiltration of M1-like macrophages (iNOS+) at the expense of M2-like macrophages (Arg1/CD68+), and an increase in CD8 + T cells in Mettl1 +/- and Mettl1flox/flox tumours compared to Mettl1+/+ tumours." (PMID 37516825, 2023). "Having confirmed the presence of CD11b‐expressing macrophages (CD11b+/CD68+) in our 3D model after 14 d by flow cytometry, we further explored the potential of ADH‐503 treatment in modulating the tumor‐immune landscape." (PMID 36417691, 2023). "In both contexts, the majority of F4/80‐positive cells infiltrating the tumour were negative for both CD68 and CD163." (PMID 35924447, 2023). "To verify that the RIME‐MLL1‐H3K4me3 axis is clinically associated with ESCC development, we performed immunohistochemistry analysis and evaluated CD68, MLL1, PD‐L1, IDO‐1, CD8 and GranB expression in tumour tissues from a cohort of ESCC patients (SYSUCC, n = 70)." (PMID 37712124, 2023). "Tumours with a low MITF expression showed an increase in the numbers of CD3D (p = 0.048), CD8A (probe 3: p = 0.01), and CD68 (two probes, p = 0.001 and p = 0.004) cells, as well as a higher expression of HLA-A (three probes: p = 0.003, p < 0.001, and p = 0.002) and HLA-B (p = 0.004)." (PMID 37240204, 2023). "LAIR-1 was multiplexed with lymphocyte markers (CD45RA, CD4, CD8, CD20, CD56), myeloid monocyte markers (CD14, CD68, CD163 for macrophages and CD66b for neutrophils), fibroblast marker (SMA), hematopoietic progenitor cells (HPC, CD34) and tumor marker (pan CK)." (PMID 36960400, 2023). "The tumor cells were weakly positive for CD68 and lysozyme, negative for CD163, and positive for CD4, which excluded rare tissue cell-derived tumors." (PMID 36871023, 2023). "Clusters with a higher CD163 expression rate compared to CD68 were only observed in blood samples from tumor patients, but not in TIL." (PMID 38322012, 2023). "Clinical analysis reveals a positive correlation between LOXL4 expression in CD68+ cells and PD-L1 levels in human HCC tissue, while high LOXL4 expression in CD68+ cells and low CD8A expression in tumor tissue serve as predictive markers for poor survival in HCC patients." (PMID 37626849, 2023). "The mean number of infiltrating CD68+ macrophages/microglia per mm2 in the tumor area in responders was 2.2-fold higher than in non-responders (621.2 ± 684.7 vs. 279.5 ± 198.1), but this difference was not statistically significant (p = 0.33)." (PMID 36694264, 2023). "Therefore, to better understand tumor regression and the influence of JOL2888 on TAMs, we examined the levels of these three key TAMs (CD68, CCL2, and iNOS)." (PMID 37941832, 2023).
tumor (continued). "In another analysis of a subgroup of patients with unresectable mCRC based on BRAF status, high tumor infiltration CD68+ macrophages had no prognostic role in BRAF mutant mCRC (data not shown)." (PMID 37302081, 2023). "Furthermore, the LMR correlated with the tumoral CD3/CD68 ratio in the surgical samples, suggesting that the LMR partly reflects anti-tumor immunity governing the TME." (PMID 37400504, 2023). "Interestingly, CD68+ TAMs have been shown to suppress cytotoxic activity of CD8+ T-cells and increase tumour growth." (PMID 37397243, 2023). "We investigated the bone remodeling markers RANK/RANKL/OPG, the endothelial glycoprotein CD146, and biomarkers of the immune environment (CD163 and CD68 of macrophages, CD4+ and CD8+ of tumor-infiltrating lymphocytes (TILs), and an immune checkpoint PD-1/PD-L1)." (PMID 36831348, 2023). "In addition, monocyte/macrophage markers (CD14, CD68, and CD163) were also lower in the tumor core of liver metastases, but CD14 and CD163 were more abundant in peritumoral regions of liver metastases than lung or peritoneal metastases." (PMID 37768208, 2023). "Thus, we conclude that CD68-positive microglia/ macrophages are a relevant source of TSPO expression/enrichment, predominantly in tumor-adjacent zones and less in solid tumor core areas." (PMID 37697350, 2023). "Next, we measured the CD68, CD86 (M1 marker) and CD163 protein levels in tumor tissues." (PMID 37875398, 2023). "Thus, the triad of CD8, CD68 and CCL18 clearly influences tumor prognosis, which corroborates our findings in the cox regression analysis." (PMID 35675033, 2022). "Another type of cells that has a role in promoting tumor development in cHL are tumor-associated macrophages (TAM), recognized by their expression of CD68 (M1 phenotype) and/or CD163 (M2 phenotype), which inhibit anti-tumor response, stimulate angiogenesis and migration of tumor cells." (PMID 35327381, 2022). "The tumor samples have been stained with CD4, CD8, CD68, and MMP9 immune stain markers." (PMID 35083113, 2022). "Regards the tumor expansion, the immune microenvironment, certain infiltrating immune cells (i.e., CD3, CD4, CD8, CD68 positive cells) were thought to play certain roles in progression-free survival (PFS) of PDAC after radical resection, yet it is need to be further verified in PDAC LTSs." (PMID 34255132, 2022). "We found no alterations in CD68 density in the hind paw skin of tumor-bearing mice (n = 17–20/group from ≥ 3 biological replicates), indicating that the IENF loss associated with MC38 injection does not elevate skin macrophage density." (PMID 35962398, 2022). "In addition, volume densities of BrdU + macrophages (CD68 + /BrdU +) and BrdU + pneumocytes (CK7 + /BrdU +) were also significantly higher in animals with orthotopic MLL-tumors compared to tumor-free controls." (PMID 35551231, 2022). "Besides, CD68 and CD163 were more co‐expressed in tumor tissues with high PTX3 expression than in tumor tissues with low PTX3 expression." (PMID 35855654, 2022). "CD68+ and CD163+ macrophage cells could be detected in tumor stroma, connective tissues, and around vessels." (PMID 35877331, 2022). "Compared with tumors with Chemo, tumors with Io+Chemo demonstrated a significantly higher ratio of M1 macrophage density in the tumor to that in the stroma (P = 0.0446), more abundant CD8+ cells in the stroma (P = 0.0335), and fewer PD-L1+CD68+ cells in both tumor and stroma." (PMID 36275670, 2022). "Furthermore, immunofluorescence double-labeling experiments demonstrated co-localization of AIF-1 and CD68 in cells within cancer nests, suggesting that AIF is mainly expressed in the cytoplasm of macrophages infiltrating the tumor tissue." (PMID 36520870, 2022).
tumor (continued). "We consistently found a clear biotinylation labeling of these cell entities in tissue sections, and confocal microscopy of tumor SCSs could confirm distinct surface biotinylation of CD45+, CD68+, CD31+, and EGFR+ tumor cells." (PMID 35217608, 2022). "The proportions of CD68+ TAMs are also consistent across different tissues except that the tumor parenchyma is moderately higher than the nontumor region (p‐value = 0.04)." (PMID 35150094, 2022). "Histopathological (not shown) and expression analyses of CD45 and CD68 confirmed tumor volume differences to be accounted for by variations in PC amounts, and not by differential accumulation of microenvironmental innate immune cells." (PMID 36172163, 2022). "In addition to the lymphoid lineage markers including CD3, CD4, CD8, CD20, CD45, CD56, and FOXP3, we also examined myeloid lineage markers such as CD14, CD68, CD34 to accurately identify the specific cell types within the tumor microenvironment of YTMA-76." (PMID 35810563, 2022). "Additionally, another recent study shows that COL1A1 inhibition in glioma cells decreased CD68+ and IBA1+ macrophages/microglia within the tumor, decreased mesenchymal transformation, and inhibited tumor growth." (PMID 36186781, 2022). "In these 8 tumors, CD68-positive macrophage-cells were the most represented cell type [median at 427.4 per mm2; range (140.4-1014.3)] and 5 out of them displayed TIM3 positivity in tumor cells (>100 cells per mm2)." (PMID 35278076, 2022). "In addition, weaker, but significant correlations of nuclear and cytoplasmic STAT1 in the tumor cells and of STAT1-positive immune cells were observed with the CD20- and CD68-positive immune cell infiltrate." (PMID 35267462, 2022). "The M-IHC panel included CD68/CD163 (macrophage cocktail) and CK to determine whether ANXA2 staining was predominantly localized to tumor cells or macrophages." (PMID 36377658, 2022). "In addition, we discovered that the percentages of CD68+CD163+ and CD68+CD206+ cells in tumor tissue were significantly higher than in the adjacent healthy tissue (ANOVA, p < 0.05)." (PMID 36230558, 2022). "Finally, we evaluated the possible immune-regulatory function of PD-L2 on CD68+ macrophages and CD4+Foxp3+ Treg cells in the tumor microenvironment in NPC." (PMID 36606190, 2022). "Interestingly, we also revealed an increase in the CD163 to CD68 ratio during the transition from IPN to invasive BTC, thereby highlighting the tumour-promoting role of M2 TAMs." (PMID 36068277, 2022). "More than 85% of PDLIM2-positive TNBC tumours expressed moderate or high CD68 expression compared to 65% of the PDLIM2 negative tumours." (PMID 36531051, 2022). "This could also be readily observed through comparison of the number of cells that expressed the macrophage markers CD68, CD86, and CD163 in paired human tumor lesions and adjacent normal tissue in the same tissue block." (PMID 35326625, 2022). "Tumor densities of CD68+ and CD163+ cells were not different in C2D1 biopsies; neither those of DC-LAMP+, IDO1+, ICAM1+ or CD31+ cells (data not shown)." (PMID 35794623, 2022). "We did not observe any significant changes in lumbar DRG CD68 density or ATF-3 expression in samples from tumor-bearing vs control mice (n = 7–12/group from ≥ 3 biological replicates)." (PMID 35962398, 2022). "Neither did we observe any correlation between the AMC and CD68 or CD163 gene expression levels in the tumor tissue (p = 0.678 and p = 0.565, respectively) nor between the AMC and soluble CD163 levels in the serum (p = 0.998)." (PMID 36051040, 2022). "The treatment regimen also decreased the presence of CD68+ immunosuppressive TAMs in stromal (non-tumor), but not tumor, regions." (PMID 35288468, 2022). "First, the messenger ribonucleic acid expression levels of CD68 were assessed from public databases and only verified by tumor tissue chips, not validated by in vivo and in vitro studies." (PMID 35550532, 2022).
tumor (continued). "Examination of lineage-specific marker expression revealed four principal clusters corresponding to tumor and glia (using the SOX2, OLIG2, GFAP markers), lymphoid cells (CD45, CD3, CD8, and CD4), myeloid cells (CD45, PU.1, CD163, CD68, and CD11b), and endothelial cells (CD31)." (PMID 35973991, 2022). "In contrast, α-SMA, a marker of activated fibroblasts, and CD68, a macrophage marker, were detected in the microenvironment of the original tumor, but not in the PDOs." (PMID 35379798, 2022). "In the tumor periphery, PTPRC+CD68+ immune cells expressed P2RY12, a marker of microglia." (PMID 36266311, 2022). "We found that CD68+ and CD206+ MØ were mainly located in the tumor stroma." (PMID 36270983, 2022). "In this study, we found that CD68 is closely related to tumor immunity in the TME and may act as a new immune checkpoint in tumor treatments in the future." (PMID 35550532, 2022). "The presence of dense CD68+ macrophage infiltrates also seem to be a prognostic finding regarding the time to recurrence and intraindividual increase in the MIB-1 index by inducing tumor regrowth." (PMID 35453901, 2022). "Subsequently, we analyzed SQLE expression and its association with biomarkers of MHC (B2M, HLA-B, HLA-C, TAP1, and TAP2), dendritic cells (BATF3), macrophages (CD68 and IL1A), type-I anti-tumor responses (CD8A and GZMB), and cell proliferation (MKI67) in 178 PAAD tissues." (PMID 35720314, 2022). "The present study also found that CD68 expression was correlated with TMB and MSI in many cancer types, which might provide probable and potential evidence for predicting the efficacy of tumor immunotherapy." (PMID 35550532, 2022). "In vivo ASK1 deficiency decreased the amount of CD68+ macrophages inside the spheroids but not the polarization of TAMs, attenuating TAM-spheroid formation and tumor peritoneal implantation." (PMID 35682890, 2022). "Lactulose treatment mitigated fibrosis; however, it had no significant (p = 0.22349) effect on the fibrosis score The mucosal and submucosal infiltration of CD68-positive cells increased in the non-tumor and tumor areas in the AOM/DSS model." (PMID 35277009, 2022). "Previous research has produced contradictory results regarding prognostic significance of CD68+ and CD163+ tumour associated macrophages (TAMs), reporting both negative and positive prognostic effect." (PMID 36114487, 2022). "Hyperactivated CD47/SIRPα and PD1/PD‐L1 signals in CD68+ TAMs in tumor tissues are negative prognostic markers for ICCs after resection." (PMID 35317832, 2022). "Second, the role of CD68 in tumor immune cell infiltration in pan-cancer was not verified by cell and animal experiments in this study." (PMID 35550532, 2022). "Interestingly, smoking was significantly correlated with a higher density of CD68- and CD204-positive macrophages in tumor stroma." (PMID 36077342, 2022). "TAMs with M1 profile usually expressed MHC-II, CD68, CD80, and CD86 and had important antitumor and pro-inflammation function, while the M2 microphage in the tumor microenvironment could play a role in pro-tumor and anti-inflammation." (PMID 34122523, 2021). "CD14+, CD68+ and CD163+ cell densities in the intratumoral tumor (IT tumor) compartment (p = 0.001; p < 0.001 and p = 0.004, respectively) and peritumoral tumor (PT Tumor) compartment (p = 0.001; p = 0.003 and p < 0.001, respectively) differed between grades of differentiation." (PMID 34194435, 2021). "Moreover, in the NOD/SCID mice bearing A549-Luc-CXCL13 cells, CXCL13 recruits CXCR5+ CD68+ macrophages to the TME, where macrophages produce secreted phosphoprotein 1 (SPP1) to promote cell migration and tumor progression." (PMID 34947813, 2021). "The increased percentage of CD68+ cells in the perivascular area in contrast to the tumor core failed to reach statistical significance (p = 0.022)." (PMID 34654395, 2021). "High expression of Wnt5a in the tumor was significantly associated with intense anti-inflammatory CD163 + TAMs, but not with CD68 + TAMs." (PMID 34566638, 2021).
tumor (continued). "M1 macrophages usually expressed MHC-II, CD68, CD80, and CD86 and had the effect of antitumor and pro-inflammation, while the M2 microphage in the tumor microenvironment could play a role in pro-tumor, immunosuppression, and anti-inflammation." (PMID 35004850, 2021). "The inflammation markers showed extremely scarce staining: CD86 did not present significant staining, and neither did CD68 but depicted unusual marking mostly at the superficial periphery of the tumor." (PMID 34830041, 2021). "In addition, myeloid cell densities in the tumor compartment were found to differ significantly based on differentiation grade (CD14 p = 0.001; CD68 p < 0.001; CD163 p < 0.001)." (PMID 34194435, 2021). "We found more CD68(+) macrophages in the tumor stroma than in the tumor nest, as well as in the non-epithelial areas of inflammation cases." (PMID 34407796, 2021). "The different expression of CD68, which is a marker of macrophages, between IDC and IDC/DCIS patients, might suggest a different TIL level between IDC and IDC/DCIS tumours, which warrants further investigation." (PMID 33335279, 2021). "In this study, BGS did not alter the total amount of TAM, however, the density of CD68+ cells at the tumor border increased in treated mice while the percentage of CD206+ from the total amount of macrophages decreased significantly." (PMID 34282238, 2021). "Immunohistochemical studies demonstrated that the tumor was positive for S100 and CD68, focal positive for neurofilaments, but negative for ERG and HMB-45." (PMID 34961529, 2021). "The tumor microenvironment is primarily composed of TILs, especially CD8+ T cells and CD68+ TAMs." (PMID 33613757, 2021). "Moreover, the expression of macrophages markers (CD68 and MAC2) and M2-like macrophages markers (CD206) significantly increased in THP-1 cells co-cultured with SPON2-overexpressing CRC tumor cells compared with the control tumor cells." (PMID 34583750, 2021). "For CD68 pan-macrophage marker, some CD68-positive (CD68(+)) cells were observed in non-epithelial areas and tumor nests, and many CD68(+) cells were observed in the tumor stroma." (PMID 34407796, 2021). "In human HCC, pro-inflammatory M1-like CD68+HLA-DR+ TAMs are more abundant in the early stages of HCC progression and undergo a phenotypic switch towards immunosuppressive M2-like CD68+ HLA-DR− TAMs once the tumor is more established." (PMID 34831182, 2021). "Stratification by TAM infiltration location revealed that a high density of CD68 + TAMs in tumor stroma and tumor islet plus stroma (but not in tumor islet cells) predicted a favorable OS." (PMID 34566638, 2021). "In the immunohistochemical studies, the tumor was positive for S100 and CD68 but focal positive for neurofilament and negative for ERG and HMB-45." (PMID 34961529, 2021). "Tumor cells were positive for CD21, CD35, CD68, vimentin, and EGFR." (PMID 34516525, 2021). "In low-risk patients, we identified significantly higher numbers of CD68 +, PD-L1 + CD68 + and PD-L1 + FOXP3 + cells in the stroma relative to tumour (n = 9) (CD68 +: p = 0.0117, PD-L1 + CD68 +: p = 0.0039, PD-L1 + FOXP3 + CD4 + p = 0.0039, paired samples Wilcoxon signed-rank test)." (PMID 34359755, 2021). "In addition, we analyzed CD8, CD68, CD206, p-STAT1 and iNOS expression to evaluate alterations in tumor micro-environment and anti-tumor immune response due to treatment." (PMID 34282238, 2021). "In this case, the cells that make up this tumor are largely S-100 protein negative, and they turn out to be CD68 positive." (PMID 34449582, 2021). "Since CD68 TAMs in the tumoural microenvironment are influenced by hypoxia, [18F]-FDG PET has demonstrated its capacity to predict hypoxia in vivo with a positive correlation between SUV and CD68 positive staining, as reported in 98 matched NSCLC specimens." (PMID 34298636, 2021). "CD39 was mostly expressed on endothelial cells, macrophages (CD68+), and some other immune cells (CD68−), but was not expressed on tumor cells (CK8+)." (PMID 34838121, 2021).